PRL (prolactin)
Diseases named in the same sentence as PRL in open-access papers (continued):
Sharing a sentence is not in itself a finding about the gene and the disease.
Hypoglycemia (16 papers, 2013 to 2025). A decreased concentration of glucose in the blood. "After the initial demonstration of SSTR2 antagonist efficacy using PRL-2903, a lower glucose nadir was targeted, to ensure that a high proportion of control rats would experience hypoglycemia." (PMID 38510652, 2024). "Early ITT responses were only observed in ATL, whereas differences in GH, prolactin, and cortisol levels were even more remarkable 30 min after hypoglycemia." (PMID 31675953, 2019). "PRL in the brain seems to exert a protective effect; icv administration of PRL protects against stress-induced hypoglycemia, ulcerogenesis, and hyperthermia." (PMID 28654010, 2017). "Additionally, a more robust hypoglycemia challenge was used to assess ZT-01 (12 U/kg insulin, achieving blood glucose in controls <3.0 mmol/L), compared to PRL-2903 (3 U/kg, achieving glucose values of 3.5 mmol/L in controls)." (PMID 38510652, 2024). "The insulin challenge dose was 12 U/kg, which was higher than the 3 U/kg dose used in the PRL-2903 experiment, selected with the intent to induce level 2 hypoglycemia (<3.0 mmol/L) in the control group, whereas level 1 hypoglycemia (3.5 mmol/L blood glucose) was achieved in the PRL-2903 study." (PMID 38510652, 2024). "These two hormones (PRL and GH) have partly the same common secretory mechanisms, such as estrogens, dopamine, TRH, ghrelin, stress or hypoglycemia." (PMID 41155234, 2025). "Basal prolactin levels were similar between groups, but responses during and 30 min after hypoglycemia were significantly higher in ATL than in NPAC (p = 0.01 and p = 0.002, respectively), as well as prolactin change during ITT (p = 0.01)." (PMID 31675953, 2019). "Within the brain, PRL dampens stress-induced activation of the HPA axis and exerts protective effects against stress, as lateral cerebroventricle administration of PRL decreases stress-induced ACTH secretion and protects against stress-induced hypoglycemia and ulcerogenesis." (PMID 27893788, 2016). "Hypoglycemia did not occur in all animals during the ITT and fewer T2D rats developed hypoglycemia with PRL-2903 treatment (44%) than with vehicle treatment (66%)." (PMID 38510652, 2024).
multiple sclerosis (16 papers, 2006 to 2025). A progressive autoimmune disorder affecting the central nervous system resulting in demyelination. "Notably, research exploring the association between yoga and prolactin levels has been limited to women with multiple sclerosis, using online tele-yoga and tele-Pilates exercise interventions via platforms such as Google Meet, Zoom, and Instagram." (PMID 38813356, 2024). "Another study that involved 45 women with multiple sclerosis who did tele-yoga and tele-Pilates for 8 weeks showed an increase in prolactin levels from 20.33 ± 11.72 ng/ml to 32.62 ± 23.84 ng/ml (P = 0.004)." (PMID 38813356, 2024). "High PRL serum levels in patients with immune-inflammatory conditions like RA, psoriatic arthritis, multiple sclerosis, and systemic lupus were reported, highlighting the relation between PRL and these diseases." (PMID 36717425, 2023). "PRL’s role in white matter injury has been studied most recently in multiple sclerosis patients and in mouse models of spinal cord injury." (PMID 35921360, 2022). "Prolactin, however, can elicit pro-inflammatory responses, and its use in the prototypical demyelinating and inflammatory condition, multiple sclerosis (MS), should thus be approached cautiously." (PMID 25889599, 2015). "In addition, the protective role of prolactin in white matter damage has been demonstrated in patients with multiple sclerosis and mouse models of spinal cord injury." (PMID 39361237, 2025). "Serum prolactin levels are increased in Huntington’s disease and multiple sclerosis, suggesting it may also be implicated in neurodegeneration." (PMID 36389068, 2022). "However, the role of PRL in tissue injury and repair mechanisms related to multiple sclerosis (MS) is still debated." (PMID 26236110, 2015). "At least one PRL was identified in seven multiple sclerosis patients (between 1 and 5 PRLs per patient) and in none of NMOSD patients." (PMID 39258257, 2024). "Prolactin is a neuroendocrine hormone that mainly regulates lactation but also acts as an inflammatory cytokine, being involved in the pathogenesis of several inflammatory diseases, such as SLE, multiple sclerosis, cancer, and periodontitis." (PMID 38139057, 2023). "However, recent findings have challenged this common view, showing that PRL does not play a crucial role in the development of experimental autoimmune encephalomyelitis, the animal model for multiple sclerosis (MS), and even protects against adjuvant induced model of rheumatoid arthritis." (PMID 26236110, 2015).
panhypopituitarism (16 papers, 2011 to 2025). Insufficient production of all the anterior pituitary hormones. "Four patients (6.2%) had combined deficiencies in TSH, FSH, LH and prolactin, while one patient (1.5%) developed panhypopituitarism following the second repeat ETS." (PMID 38748309, 2024). "The most common cause of panhypopituitarism was Sheehan syndrome in PRL deficient patients and surgery in PRL sufficient patients." (PMID 38700812, 2024). "Prolactin level was 9000 ng/ml (2.5-11 ng/ml); the other hormone measurements were suggestive of an associated panhypopituitarism." (PMID 24398140, 2014). "Similarly, the presence of panhypopituitarism-an indirect indicator of a large and invasive tumor-was associated with greater tumor size and higher PRL levels in that pediatric series." (PMID 40599499, 2025). "When patients were divided into 2 groups according to PRL deficiency, PRL-deficient male patients with panhypopituitarism had lower sexual function scores compared to the control group, but PRL sufficient male patients had similar sexual function scores compared to the control group." (PMID 38700812, 2024). "Regarding the fifth deficiency, i.e. prolactin deficiency, the low efficiency of the lectin pathway (resulting in low MBL level) could be rather associated with severity of the disease such as panhypopituitarism than with low concentration of prolactin by itself." (PMID 37122698, 2023). "On the other hand, some authors proposed gender-dependent thresholds for basal PRL levels that are capable of defining PRL sufficiency in individuals with panhypopituitarism." (PMID 39172174, 2024). "In patients with panhypopituitarism, the peak prolactin responses to TRH were significantly lower than healthy controls." (PMID 39037546, 2024). "In this study, median basal PRL levels were significantly lower in patients with panhypopituitarism compared to healthy volunteers (3.36 ng/ml vs. 10.1 ng/ml)." (PMID 39172174, 2024). "Sequentially, a gross total resection was performed resulting in normalization of PRL levels and panhypopituitarism." (PMID 36157469, 2022). "Male gender, increased PRL levels, and the presence of panhypopituitarism at diagnosis are closely related to macroprolactinomas in children and adolescents." (PMID 32849307, 2020). "Male gender, the prolactin (PRL) level at diagnosis, and the presence of panhypopituitarism were positively correlated with maximum tumor diameter (r = 0.443, P = 0.026; r = 0.710, P < 0.001; and r = 0.623, P = 0.001, respectively)." (PMID 32849307, 2020). "Blood tests revealed increased inflammatory markers, a serum prolactin of 9000 ng/ml (2.5-11 ng/ml) and panhypopituitarism." (PMID 24398140, 2014). "Free T3, TSH, PRL and PRL responses to TRH stimulation were lower in patients with panhypopituitarism compared to the control group." (PMID 38700812, 2024). "Only recently have new cutoff values been suggested for men and women via the TRH stimulation test, which assesses PRL responses at 20 and 60 min after IV administration of 200 μg TRH in 48 patients with panhypopituitarism and 20 healthy controls." (PMID 39425884, 2024). "Panhypopituitarism can be differentiated from isolated CCH by normal levels of ACTH, cortisol, IGF1/IGFBP3, LH, FSH, and prolactin." (PMID 22606512, 2011). "The presence of a macroprolactinoma was correlated with male gender (r = 0.443, P = 0.026), high PRL level at diagnosis (r = 0.710, P < 0.001), and the presence of panhypopituitarism (r = 0.623, P = 0.001), but not with age at diagnosis, BMI SDS, height SDS, and the Ki-67 index." (PMID 32849307, 2020).
epilepsy (15 papers, 2019 to 2026). A brain disorder characterized by episodes of abnormally increased neuronal discharge resulting in transient episodes of sensory or motor neurological dysfunction, or psychic dysfunction. "We assessed the association between PRL levels and clinical symptoms, such as prodromal symptoms, psychobehavioral abnormalities, and epilepsy." (PMID 41163354, 2025). "Due to this, prolactin serves as both a diagnostic biomarker and a marker of acute hypothalamic–pituitary stress activation in the setting of epilepsy." (PMID 41323226, 2025). "Elevated levels of prolactin have long been recognized as a hallmark of both epilepsy and ECT." (PMID 39363047, 2025). "VPA has also been found to cause an increase in the level of PRL in mice and epilepsy patients." (PMID 34285917, 2021). "Emerging evidence underscores the complex bidirectional interplay between epilepsy, antiepileptic drugs (AEDs), and sex steroid hormones; particularly progesterone, testosterone, and prolactin, which influence both seizure threshold and reproductive function." (PMID 41323226, 2025). "Understanding the fluctuations in the prolactin levels during seizures can provide valuable insights into the basic mechanisms of epilepsy and may lead to the development of new treatment approaches." (PMID 38050507, 2023). "Prolactin is also raised intracranially in certain males and females with epilepsy." (PMID 38050507, 2023). "In addition, prolactin which is secreted from the hypothalamus and is sometimes used as a biomarker of epilepsy can be often related to other conditions, such as milk production, breast development, and pituitary tumors." (PMID 34827090, 2021). "An elevation of serum prolactin two times baseline can be taken as a predictor of a true epilepsy." (PMID 31403020, 2019). "Besides, the level of prolactin (PRL) will increase in patients with epilepsy, so epilepsy could disrupt the hormone secretion balance of the HPO system by affecting the negative feedback of PRL." (PMID 34992582, 2021). "It has been suggested that epilepsy directly affects the hypothalamic–pituitary axis, resulting in altered levels of GnRH, LH, FSH, PRL, and downstream hormones such as estrogen, testosterone, and DHEA." (PMID 41323226, 2025). "In short, epilepsy can affect the HPO axis through abnormal discharge, change the level of the central nervous system neurotransmitter, and change the level of PRL, leading to PCOS or other reproductive endocrine disorders in patients." (PMID 34992582, 2021). "Historically, PRL levels recorded shortly after a seizure (within 20 mins) have been used to assess the etiology (epileptic or non-epileptic) of an epilepsy spell." (PMID 38711940, 2024). "In this study, we found that young male epilepsy patients taking VPA showed a marked decrease in sperm concentration, total number of sperm, and percentage of sperm with forward movement as well as a significant increase in PRL levels after 6 months of treatment." (PMID 34285917, 2021).
insomnia (15 papers, 2008 to 2024). A sleep disorder characterized by difficulty in falling asleep and/or remaining asleep. "A retrospective study reported that 42.3% of hospitalized patients admitted for mental illness and sleep disorders had elevated PRL levels and suggested an association between elevated PRL levels and excessive daytime sleepiness, which may be caused by nocturnal insomnia." (PMID 38572480, 2024). "In the present study, the expression of prolactin increased under warm acupuncture, which is one of the ways to alleviate insomnia." (PMID 32249904, 2020). "Among them, prolactin protein prolactin (prelp), which has been shown to be closely related to insomnia treatment, is the focus of our future research." (PMID 32249904, 2020). "Although the GRADE approach showed the quality of evidence were “low” in insomnia and headaches, other outcomes were from “moderate” to “high”, especially the quality of evidence in prolactin level normalization were all “high”." (PMID 23936389, 2013). "Consequently, we highlighted the potentially interesting functions of the novel associations for PRL (6p22.3) between AD and snoring, as well as the focused PTPMT1(11p11.2) and KAT8(16p11.2) regions shared between AD and insomnia or sleep duration." (PMID 35656316, 2022). "Our study revealed that compared to patients without sleep disorders, those with insomnia seemed to have lower PRL levels." (PMID 38572480, 2024). "Compared with patients without sleep disorders, insomnia patients had higher PRL levels." (PMID 38572480, 2024).
Central hypothyroidism (14 papers, 2016 to 2025). A type of hypothyroidism due to an insufficient stimulation of an otherwise normal thyroid gland. "Mutations in the POU1F1 gene are characterized by growth hormone (GH), thyrotropin, and prolactin deficiencies, commonly presenting with growth retardation and central hypothyroidism." (PMID 31316460, 2019). "Up to now, systematic IGSF1 mutation analysis has not been performed in larger cohorts of patients with transient or persistent GH deficiency in combination with central hypothyroidism and low PRL levels." (PMID 26757742, 2016). "Because of the combination of central hypothyroidism, GH deficiency, low PRL status, and normal pituitary imaging, genetic testing of PROP1 and POU1F1 was performed, but no mutations were found." (PMID 26757742, 2016). "All male patients showed central hypothyroidism and 59% were prolactin deficient." (PMID 26840047, 2016). "Hormonal assay showed central hypothyroidism and elevated level of prolactin." (PMID 37404438, 2023). "Endocrine evaluation was notable for a mildly elevated prolactin of 51.1 ng/ml (normal range: 4.8-23.3 ng/mL), felt to be due to stalk effect, and decreased free T4 of 0.63 ng/dL (normal range: 0.80-1.70 ng/dL), the latter suggesting central hypothyroidism." (PMID 34925233, 2021). "Male children with an idiopathic combined GH, PRL, and TSH deficiency, showing persistent central hypothyroidism but transient GH deficiency upon retesting at adult height, should be screened for mutations in the IGSF1 gene, especially when macro-orchidism and/or hypoprolactinemia are present." (PMID 26757742, 2016). "Normalization of cortisol and prolactin following correction of the AV shunt in our patient supports this hypothesis, although her ongoing central hypothyroidism raises concern that this condition can result in permanent deficits." (PMID 27651959, 2016). "We advise genetic evaluation of all patients with central hypothyroidism of unknown cause for IGSF1 mutations, especially when accompanied by an X-linked inheritance pattern, prolactin or GH deficiency, disharmonious pubertal development, macroorchidism, or delayed adrenarche." (PMID 26840047, 2016). "Patients with functional PA are prone to central hypothyroidism, or varying degrees of FT3 and FT4 changes, due to the complex effects of growth hormone, cortisol, and prolactin on the hypothalamic-pituitary-thyroid axis." (PMID 37020857, 2023). "Thyrotropin-releasing hormone (TRH) stimulation test confirmed central hypothyroidism with a poor TSH response and normal prolactin secretion." (PMID 28262687, 2017). "In patients with central hypothyroidism, it is recommended, at the diagnosis, to perform the following tests: morning cortisol and ACTH, LH, FSH, prolactin, IGF-1, testosterone in males, estradiol in females and MRI of the hypothalamus-pituitary region, unless contraindicated." (PMID 35407442, 2022).
craniopharyngioma (14 papers, 2009 to 2025). A benign, partly cystic, epithelial tumor of the sellar region, presumably derived from Rathke pouch epithelium. "A brain MRI showed a mass in favor of macroadenoma, craniopharyngioma, or meningioma, and elevated prolactin level led to the diagnosis of macroprolactinoma." (PMID 39121253, 2024). "Among the remaining group of 36, two cases of suspected prolactinoma (serum PRL <20,000mU/1) and two cases of surgically confirmed cranio-pharyngioma were observed." (PMID 38250535, 2023). "In addition, 1 patient with germinoma and 1 patient with craniopharyngioma had elevated PRL levels (29.03 ng/mL and 58.54 ng/mL)." (PMID 27118970, 2016).
Hyperinsulinemia (14 papers, 2018 to 2025). An increased concentration of insulin in the blood. "Prolactin is linked to modifications in the intracellular response to HS by triggering heat shock protein gene expression; it participates in mechanisms regulating the increased water and electrolyte demands that occur in heat-stressed animals; and it mediates HS-induced hyperinsulinemia." (PMID 37467251, 2023). "Hyperinsulinism and elevated prolactin levels were observed in those patients with excessive growth." (PMID 38152125, 2023). "Our previous discoveries on ovarian impacts of HS-induced hyperinsulinemia and a documented relationship between insulin and PRL provided the rationale for our supposition." (PMID 35772766, 2022). "A biochemical workup revealed hyperinsulinemia and androgen excess with elevated prolactin levels." (PMID 30250766, 2018). "Elevated prolactin levels may also normalize IGF-1 levels in GHD patients without hyperinsulinism." (PMID 38152125, 2023).
pituitary apoplexy (14 papers, 2012 to 2026). A rare, potentially life-threatening disorder caused by acute ischemic infarction or hemorrhage in the pituitary gland. "Consistent with these concepts, in our literature review, we found 43 cases of pituitary apoplexy associated with the use of DAs (cabergoline and bromocriptine), and the majority of them were PRL-secreting (90%) PitNETs, while the remaining PitNETs were secreting GH or TSH." (PMID 40725781, 2025). "Receiver operating characteristic curve analysis revealed that the optimal prolactin level that supports the diagnosis of pituitary apoplexy was 7.5 ng/mL (AUC = 0.75250, 50% sensitivity, 100% specificity)." (PMID 41735703, 2026). "The patient with PRL-secreting PitNET had pituitary apoplexy at onset and underwent transsphenoidal intervention." (PMID 38248047, 2024). "Long-term monitoring should be planned to adjust the therapeutic doses according to the prolactin level, to detect complications related to the increase in tumor size or pituitary apoplexy, and to better understand the problems induced by estrogens in case of pregnancy or contraception." (PMID 36540468, 2022). "In our view, the most plausible explanation for the present case is that the pituitary apoplexy with hemorrhage of the macroadenoma at its initial presentation, with necrosis of the tumor lactotroph cells, provoked the normalization of the circulating PRL levels, which were previously elevated." (PMID 39051300, 2024). "Magnetic resonance imaging (MRI) revealed a large sellar/suprasellar lesion, and hormonal profile confirmed elevated insulin-like growth factor 1 (IGF-1) with low levels of prolactin, luteinizing hormone (LH), follicle-stimulating hormone (FSH), and testosterone, consistent with pituitary apoplexy." (PMID 41625684, 2026).